MAN2C1 (mannosidase alpha class 2C member 1)
Description:
Cleaves alpha 1,2-, alpha 1,3-, and alpha 1,6-linked mannose residues on cytoplasmic free oligosaccharides generated by N-glycoprotein degradation pathways.
Synonyms: MANA; MANA1; CDDG2; MAN6A8
Tractability: PROTAC: ubiquitination databases record sites on it; its protein half-life has been measured.
Gene: Protein-coding gene on chromosome 15 (75,355,207 to 75,368,656, reverse strand). Ensembl gene ENSG00000140400.
Subcellular location: Cytoplasm
Pathways (Reactome):
Metabolism: Lysosomal oligosaccharide catabolism
Gene Ontology:
Molecular function: alpha-mannosidase activity; carbohydrate binding
Biological process: oligosaccharide catabolic process; carbohydrate metabolic process; mannose metabolic process
Cellular component: cytoplasm; cytosol
Genetic constraint (gnomAD): Loss-of-function variants: 115 observed, 132.51 expected, observed/expected ratio (o/e) 0.87, 90% interval 0.75 to 1.01. The upper end of that interval is the gene's LOEUF score, 1.01, which puts it in group 4 of 6, group 1 being the genes least tolerant of losing a copy. Missense variants: 1,361 observed, 1,375.8 expected, observed/expected ratio (o/e) 0.99, 90% interval 0.94 to 1.03. Synonymous variants: 567 observed, 566.09 expected, observed/expected ratio (o/e) 1, 90% interval 0.93 to 1.07.
Gene-disease validity (ClinGen):
ClinGen rates the evidence that MAN2C1 causes each of these diseases.
congenital disorder of deglycosylation 2 (autosomal recessive): Moderate.
Homologues: Orthologues: chimpanzee MAN2C1 (99% identical), macaque MAN2C1 (98% identical), pig MAN2C1 (92% identical), dog MAN2C1 (90% identical), mouse Man2c1 (90% identical), rat Man2c1 (89% identical), guinea pig MAN2C1 (83% identical), tropical clawed frog man2c1 (64% identical), zebrafish man2c1 (61% identical). Paralogues in human: MAN2A2 (17% identical), MAN2A1 (16% identical), MAN2B1 (15% identical), MAN2B2 (15% identical).
Diseases named in the same sentence as MAN2C1 in open-access papers:
MAN2C1 is named in the same sentence as 19 diseases in open-access papers, as found by Europe PMC text mining. Sharing a sentence is not in itself a finding about the gene and the disease. The quoted sentences say what the papers report.
breast carcinoma (4 papers, 2017 to 2022). "In our analysis, each risk allele of variants rs8027365 and rs67079557 contribute to a reduction in the expression of MAN2C1 transcript, suggesting hence a protective role of MAN2C1 in breast cancer initiation." (PMID 35061909, 2022). "Of these, genes hypothesized to have a tumor-suppressor function included LINC00886, MAN2C1, SNUPN, and STC1, while YBEY, SEMA4A, and MUTYH may have an oncogenic role in breast carcinogenesis based on their associations with breast cancer risk." (PMID 32139696, 2020).
prostate carcinoma (3 papers, 2020 to 2022). A carcinoma that arises from epithelial cells of the prostate gland. "Furthermore, PTEN-positive prostate cancers frequently overexpress MAN2C1, and MAN2C1 expression in prostate cancer significantly correlates with reduced recurrence-free survival." (PMID 33105713, 2020). "Moreover, MAN2C1 negatively regulates PTEN in prostate cancer, thereby promoting tumor development." (PMID 34544412, 2021). "With respect to our results related with MAN2C1 gene, it has been shown that the gene may inhibit the function of tumor suppressor gene PTEN in breast and prostate cancer and another study found that the gene may have a protective role in cancer initiation with respect of progression." (PMID 35061909, 2022).
Intellectual disability (2 papers, 2016 to 2025). "Six individuals, including two fetuses, with biallelic variants in MAN2C1 reported dysmorphic facial features, congenital anomalies, variable degrees of intellectual disability, and brain anomalies." (PMID 41191133, 2025). "Our population-based analyses suggest that MAN2C1 may contribute to the verbal difficulties observed in microduplications and to the intellectual disability of microdeletion syndromes, whose characteristic dosage increment and removal may affect different brain areas." (PMID 27355585, 2016).
Cognitive impairment (1 paper, 2016). Abnormal cognition is characterized by deficits in thinking, reasoning, or remembering. "Our findings therefore suggest that MAN2C1 can be an important contributor to the cognitive impairments of both microdeletions and microduplications." (PMID 27355585, 2016).
even-plus syndrome (1 paper, 2025). "For example, MAN2C1 is associated with congenital disorder of deglycosylation 2 (MIM #619775), GPHN with molybdenum cofactor deficiency C (MIM #615501), LRP2 with Donnai–Barrow syndrome (MIM #222448), and HSPA9 with Even-plus syndrome (MIM #616854)." (PMID 40282865, 2025).
melanoma (1 paper, 2021). A malignant, usually aggressive tumor composed of atypical, neoplastic melanocytes. "MAN2B1 and ST3GAL4 exhibited higher expression in melanoma patients, and MAN2C1 was downregulated in tumor tissues." (PMID 34544412, 2021). "Among different cancers, MAN2C1 is moderately expressed in melanoma." (PMID 34544412, 2021).
Obesity (1 paper, 2016). Accumulation of substantial excess body fat. "This set of genes includes the X-linked Cul4b, which has previously been associated with syndromic obesity in humans, and Man2c1 which has been associated with a gonadal fat pad QTL on chromosome 9 in mice." (PMID 27506198, 2016).
polymicrogyria (1 paper, 2023). A developmental brain abnormality characterized by an excessive amount of small convolutions on the surface of the brain and cognitive dysfunction. "In addition to detecting pathogenic variants in genes previously linked to polymicrogyria (eg, ADGRG1/GPR56, SCN3A, TUBB2B), we discovered 6 genes linked to polymicrogyria for the first time (QRICH1, TMEM161B, PANX1, KIF26A, SCN2A, and MAN2C1)." (PMID 37486637, 2023).
posttraumatic stress disorder (1 paper, 2016). "Nevertheless, an indication of such function in the brain is given by previous findings showing that MAN2C1 is over-expressed in patients with posttraumatic stress disorder, and that such psychopathology presents reduced apoptosis associated with defects in signal plasticity." (PMID 27355585, 2016).
cancer (5 papers, 2020 to 2025). A tumor composed of atypical neoplastic, often pleomorphic cells that invade other tissues. "Out of them, we selected 4 communities associated with genes CASP8, MAN2C1, BTN3A2 and ARL17A which are all reported in literature as possibly involved in cancer." (PMID 35061909, 2022). "In addition, we found that MAN1A1 and MAN2C1 are downregulated in most cancer types, whereas B4GALT1 and B4GALT3–5 are upregulated in most cancer types." (PMID 41093273, 2025).
tumor (5 papers, 2016 to 2021). "An additional function of MAN2C1, independent of N-glycosylation, is apoptosis signalling and tumour growth." (PMID 27355585, 2016).
MAN2C1 also shares sentences with these, for which no sentence is quoted: infection (5 papers); brain disease (1); developmental and epileptic encephalopathy (1); esophageal carcinoma (1); microdeletion syndromes (1); nasopharyngeal carcinoma (1); thymoma (1); Ververi-Brady syndrome (1).